SMARCD1 (SWI/SNF related BAF chromatin remodeling complex subunit D1)
Description:
Involved in transcriptional activation and repression of select genes by chromatin remodeling (alteration of DNA-nucleosome topology). Component of SWI/SNF chromatin remodeling complexes that carry out key enzymatic activities, changing chromatin structure by altering DNA-histone contacts within a nucleosome in an ATP-dependent manner. Belongs to the neural progenitors-specific chromatin remodeling complex (npBAF complex) and the neuron-specific chromatin remodeling complex (nBAF complex). During neural development a switch from a stem/progenitor to a postmitotic chromatin remodeling mechanism occurs as neurons exit the cell cycle and become committed to their adult state. The transition from proliferating neural stem/progenitor cells to postmitotic neurons requires a switch in subunit composition of the npBAF and nBAF complexes. As neural progenitors exit mitosis and differentiate into neurons, npBAF complexes which contain ACTL6A/BAF53A and PHF10/BAF45A, are exchanged for homologous alternative ACTL6B/BAF53B and DPF1/BAF45B or DPF3/BAF45C subunits in neuron-specific complexes (nBAF). The npBAF complex is essential for the self-renewal/proliferative capacity of the multipotent neural stem cells. The nBAF complex along with CREST plays a role regulating the activity of genes essential for dendrite growth (By similarity). Has a strong influence on vitamin D-mediated transcriptional activity from an enhancer vitamin D receptor element (VDRE). May be a link between mammalian SWI-SNF-like chromatin remodeling complexes and the vitamin D receptor (VDR) heterodimer. Mediates critical interactions between nuclear receptors and the BRG1/SMARCA4 chromatin-remodeling complex for transactivation. Interacts with AKIRIN2 (By similarity).
Synonyms: BAF60A; Rsc6p; CRACD1; CSS11
Tractability: Small molecule: a structure with a bound ligand is known. PROTAC: UniProt records ubiquitination sites on it; ubiquitination databases record sites on it; its protein half-life has been measured.
Gene: Protein-coding gene on chromosome 12 (50,085,200 to 50,100,712, forward strand). Ensembl gene ENSG00000066117.
Subcellular location: Nucleus
Subcellular location (Human Protein Atlas): Nucleoplasm; Vesicles
Pathways (Reactome):
Chromatin organization: Formation of neuronal progenitor and neuronal BAF (npBAF and nBAF); Formation of the canonical BAF (cBAF) complex; Formation of the embryonic stem cell BAF (esBAF) complex; Formation of the non-canonical BAF (ncBAF) complex; Formation of the polybromo-BAF (pBAF) complex; RMTs methylate histone arginines
Gene expression (Transcription): RUNX1 interacts with co-factors whose precise effect on RUNX1 targets is not known; Regulation of endogenous retroelements by Piwi-interacting RNAs (piRNAs)
Developmental Biology: Regulation of MITF-M-dependent genes involved in pigmentation
Gene Ontology:
Molecular function: ATP-dependent chromatin remodeler activity; molecular adaptor activity; protein binding; transcription coactivator activity; transcription coregulator activity; chromatin binding; signaling receptor binding
Biological process: chromatin remodeling; transcription initiation-coupled chromatin remodeling; negative regulation of cell differentiation; positive regulation of cell differentiation; positive regulation of cell population proliferation; positive regulation of double-strand break repair; positive regulation of myoblast differentiation; positive regulation of stem cell population maintenance; positive regulation of T cell differentiation; regulation of G0 to G1 transition; regulation of G1/S transition of mitotic cell cycle; regulation of mitotic metaphase/anaphase transition; regulation of nucleotide-excision repair; regulation of transcription by RNA polymerase II; cellular response to fatty acid; nucleosome disassembly; positive regulation of DNA-templated transcription
Cellular component: nucleoplasm; nucleus; SWI/SNF complex; brahma complex; chromatin; GBAF complex; kinetochore; nBAF complex; npBAF complex; nuclear matrix; RSC-type complex
Genetic constraint (gnomAD): Loss-of-function variants: 14 observed, 64.56 expected, observed/expected ratio (o/e) 0.22, 90% interval 0.14 to 0.34. The upper end of that interval is the gene's LOEUF score, 0.34, which puts it in group 1 of 6, group 1 being the genes least tolerant of losing a copy. Missense variants: 382 observed, 601.84 expected, observed/expected ratio (o/e) 0.63, 90% interval 0.58 to 0.69. Synonymous variants: 232 observed, 225.55 expected, observed/expected ratio (o/e) 1.03, 90% interval 0.92 to 1.15.
Homologues: Orthologues: chimpanzee SMARCD1 (100% identical), dog SMARCD1 (100% identical), pig SMARCD1 (100% identical), guinea pig SMARCD1 (99% identical), mouse Smarcd1 (99% identical), rabbit SMARCD1 (97% identical), rat Smarcd1 (93% identical), macaque SMARCD1 (92% identical), tropical clawed frog asic1 (90% identical), zebrafish smarcd1 (89% identical), Drosophila melanogaster Bap60 (65% identical), Caenorhabditis elegans ham-3 (47% identical), and 1 more. Paralogues in human: SMARCD3 (69% identical), SMARCD2 (66% identical).
Diseases named in the same sentence as SMARCD1 in open-access papers:
SMARCD1 is named in the same sentence as 43 diseases in open-access papers, as found by Europe PMC text mining. Sharing a sentence is not in itself a finding about the gene and the disease. The quoted sentences say what the papers report.
breast carcinoma (7 papers, 2012 to 2024). "To test if Smarcd1 expression could modify cellular processes associated with breast cancer progression in vitro, we created 6DT1 cells with knockdown (KD) or overexpression (OE) of Smarcd1, as well as appropriate control lines shScr or empty vector (EV), respectively." (PMID 38410477, 2024). "More specifically, SMARCD1 functions as a essential expression-restricted modifier in ER+/HER2-enriched breast cancer metastasis through the regulation of splicing." (PMID 39390150, 2024). "To investigate the role of SMARCD1 in metastatic breast cancer cells, we performed co-immunoprecipitation (co-IP) followed by proteomic analysis of lysates from 6DT1 Smarcd1 OE cells grown in monolayer culture." (PMID 39390150, 2024). "To investigate the role of SMARCD1 in metastatic breast cancer cells, we performed co-immunoprecipitation followed by proteomic analysis of lysates from 6DT1 Smarcd1 OE cells grown in monolayer culture." (PMID 38410477, 2024). "More specifically, SMARCD1 functions as a Goldilocks modifier in ER+/HER2-enriched breast cancer metastasis through the regulation of splicing." (PMID 38410477, 2024). "Examples include mutations in the ARID1A gene occurring in a subset of ovarian cancers and breast cancers along with mutations in the MLL2, MLL3, SMARCD1, NCOR1 and ARID1B genes found in a subset of breast cancers." (PMID 25468711, 2015). "The direct targets of the miR-99 family are the chromatin remodeling factors SMARCA5, SMARCD1 and the growth regulatory kinase mTOR, which is also an important pathway activated in breast cancer." (PMID 22438871, 2012). "Despite the minor effects observed on gene expression, we next assessed if Smarcd1 expression might modulate chromatin structural changes in breast cancer cells." (PMID 38410477, 2024). "Other miRNAs recently implicated in breast cancer include miR-100, shown to target SMARCA5, SMARCD1, and BMPR2 genes, which directly influence tumor cell proliferation, and miR-30c, known to target TWF1 and IL-11, both of which are expressed in the MaSC/basal lineage." (PMID 26080807, 2015). "However, both high and low levels of Smarcd1 expression significantly reduced the number of metastatic nodules on the lungs, suggesting that tight regulation of Smarcd1 expression facilitates breast cancer metastasis in mice." (PMID 38410477, 2024). "Specifically, small perturbations in Smarcd1 expression significantly reduce metastasis in mouse models and alter splicing programs relevant to the ER+/HER2-enriched breast cancer." (PMID 39390150, 2024). "Several cancer-associated chromatin remodeling factors other than BAF155 have already been identified in breast cancer; for example, ARID1A, ARID1B, SMARCD1, PBRM1, BAF60A and BRG1." (PMID 25927994, 2014). "Based on these findings, we hypothesized that the direct regulation of the Smarcd1 transcript by NANOS1, PUM2, and CPSF4 may be necessary for the metastasis of breast cancer cells." (PMID 38410477, 2024). "In the case of Smarcd1, small perturbations in its expression level significantly reduce metastasis in laboratory mouse models and alter splicing programs relevant to the ER+/HER2-enriched breast cancer subtype." (PMID 38410477, 2024). "The “Goldilocks”-like phenomenon was also observed for SMARCD1 in some subtypes of human breast cancer, suggesting that this result is not merely an artifact of laboratory model systems." (PMID 38410477, 2024). "The “essential expression-restricted”-like phenomenon was also observed for SMARCD1 in some subtypes of human breast cancer, suggesting that this result is not merely an artifact of laboratory model systems." (PMID 39390150, 2024). "Given that positive and negative modulation of Smarcd1 expression in mouse mammary cancer cell lines resulted in increased tumorsphere formation and alternative splicing of a common clinically relevant gene set, we next sought to determine if changes in Smarcd1 expression modify metastasis in vivo." (PMID 38410477, 2024).
atherosclerosis (5 papers, 2017 to 2025). A disease characterized by the build-up of fatty material and calcium deposition in the arterial wall resulting in partial or complete occlusion of the arterial lumen. "Endou, Hdac7, Senp1, Olfr286, Olfr285, Nckap5l, Smarcd1, Lima1, Fam186a, and Espl1 are probable candidate genes for distal Chr15 atherosclerosis QTL (Ath53)." (PMID 36078077, 2022). "In other words, fasting and high fat/cholesterol diet both induce SMARCD1, but suppress steatosis and induce hypercholesterolemia/atherosclerosis, respectively." (PMID 28868154, 2017).
gastric cancer (5 papers, 2016 to 2023). A primary or metastatic malignant neoplasm involving the stomach. "Of particular clinical relevance, SMARCD1 is markedly upregulated in the gastric tissues of patients with gastric inflammation and also gastric cancer, and high SMARCD1 expression is associated with shorter patient survival, independent of TNM staging." (PMID 32206186, 2020). "Studies reported that miR-490 inhibits bladder cancer proliferation by targeting c-Fos, miR-490-3p could directly target nanog in mouse embryonic stem cell, and miR-490-3p exert suppressor in growth and metastasis on gastric cancer cells through directly targeting SMARCD1." (PMID 26843615, 2016).
bladder cancer (4 papers, 2016 to 2025). "There have been studies suggesting that BAF60A (it is encoded by the SMARCD1) also plays a role in regulating metabolism in bladder cancer." (PMID 39779467, 2025). "In the present study, we confirmed that knockdown of SMARCD1 and overexpression of miR‐99a‐5p induced senescence in bladder cancer cell lines." (PMID 35148461, 2022). "In summary, tumor‐suppressive miR‐99a‐5p induced cellular senescence in gemcitabine‐resistant bladder cancer cells by targeting SMARCD1." (PMID 35148461, 2022). "The overexpression of miR‐99a‐5p and the downregulation of SMARCD1 in bladder cancer cells could effectively inhibit the formation and growth of bladder cancer in vivo." (PMID 39779467, 2025). "We next examined the relationship between SMARCD1 expression levels in the TCGA cohort: SMARCD1 expression was significantly elevated in bladder cancer specimens compared to adjacent noncancerous tissues (P < 0.0001)." (PMID 35148461, 2022).
ovarian cancer (4 papers, 2015 to 2022). A primary or metastatic malignant neoplasm involving the ovary. "MiR‐490‐3p plays a tumour suppressor role in epithelial ovarian cancer by targeting CDK1 regulation and influencing SMARCD1 and cyclin D1 (CCND1) expressions." (PMID 28598010, 2017). "In summary, we believe that DLEU1 promotes the pathogenesis and development of epithelial ovarian cancer through its interaction with miR‐490‐3p, thereby altering the expression of the miR‐490‐3p target genes, that is, CDK1, CCND1 and SMARCD1, as well as the expression of MMP2, Bcl‐xLand P70S6K." (PMID 28598010, 2017).
endometriosis (2 papers, 2020 to 2021). The growth of functional endometrial tissue in anatomic sites outside the uterine body. "Using the online public databases, we focused on SMARCD1 involved in the pathogenesis of endometriosis." (PMID 32299427, 2020). "We speculated that SMARCD1 supression may induce tumorigenesis in endometriosis." (PMID 32299427, 2020).
glioblastoma (2 papers, 2021 to 2025). The most malignant astrocytic tumor (WHO grade IV). "Next, we intended to testify the prohibitive effects of Smarcd1 on glioblastoma growth in vivo; four groups of U87 lentivirus-transfected cells were harvested, and then, a total of 5 × 106 cells were implanted subcutaneously in the flank of nude mice." (PMID 33190170, 2021). "We then employed flow cytometry to evaluate the role of Smarcd1 in glioblastoma cell cycle for the reason that cell cycle arrest had a close correlation with suppressed cell propagation." (PMID 33190170, 2021). "Low expression of Smarcd1 was observed in glioblastoma cell lines and in patients with high-grade glioma." (PMID 33190170, 2021). "The findings here demonstrated that overexpression of Smarcd1 reduced cell proliferation, invasion and chemoresistance of glioblastoma." (PMID 33190170, 2021). "In the present study, we investigated the tumor suppressor role of Smarcd1 in human glioblastoma in vitro and in vivo." (PMID 33190170, 2021). "Transwell assays were employed here to detect the motility of Smarcd1 upregulated or downregulated glioblastoma cells." (PMID 33190170, 2021). "To explore the role of Smarcd1 in human glioblastoma, we first determined its differential expression compared with normal brain tissues and astrocytes." (PMID 33190170, 2021). "After acquisition of 4 lentivirus-mediated stable transfection glioblastoma cell lines, namely knockdown control cell (kd-nc), knockdown Smarcd1 cell (kd-sm), overexpression control cell (over-nc), and overexpression Smarcd1 cell (over-sm), subsequent gene function analysis was conducted." (PMID 33190170, 2021). "However, treatment with Notch1 inhibitor DAPT restored the proliferation and migration abilities induced by low expression of Smarcd1, suggesting that downregulated Smarcd1 aggravated glioblastoma malignancy potentially via enabled Notch1 pathway." (PMID 33190170, 2021). "Smarcd1 is an indispensable subunit of the SWI/SNF family, and we accordingly hypothesized that Smarcd1 restrained glioblastoma cell proliferation and invasion potentially by regulation of Notch1 pathway." (PMID 33190170, 2021). "Similarly, we employed qRT-PCR and western blot to analyze the relative expression of Smarcd1 between glioblastoma cell lines (U87 and U251) and human astrocyte (HA)." (PMID 33190170, 2021). "Hence, the crosstalk between Smarcd1 and Notch1, which formed a feedback loop, was crucial in regulation of glioblastoma malignant phenotypes." (PMID 33190170, 2021). "Taken together, Smarcd1 had a vital role in inhibiting glioblastoma growth." (PMID 33190170, 2021). "Breaking up the malignant feedback loop between Smarcd1 and Notch1 may be a potential target in treating glioblastoma." (PMID 33190170, 2021). "The crosstalk between Smarcd1 and Notch1 contributed to the malignancy of glioblastoma and break up of this feedback loop may be a potential therapeutic target for glioblastoma treatment." (PMID 33190170, 2021). "Furthermore, targeting Smarcd1 could be a potential strategy for human glioblastoma treatment." (PMID 33190170, 2021). "However, the inhibitory role of Smarcd1 in human glioblastoma cells has not been well illustrated." (PMID 33190170, 2021). "However, whether or not the expression of Smarcd1 is dysregulated in glioblastoma is still unknown and the potential mechanism of Smarcd1 in regulating the malignant phenotypes of glioblastoma is urgent to be discovered." (PMID 33190170, 2021).
lung carcinoma (2 papers, 2021). "Hong and his colleagues demonstrated that the expression of Smarcd1 sensitized lung cancer cells to chemotherapy drug-induced apoptosis via the inhibition of miR-7." (PMID 33190170, 2021).
asthma (1 paper, 2020). "Age appears to modulate the association of SMARCD1 with asthma control in subjects taking inhaled corticosteroids." (PMID 31992292, 2020). "First, age appears to modulate the association of SMARCD1 with chronic asthma control." (PMID 31992292, 2020). "However, our strongest evidence indicates that increasing SMARCD1 is associated with worsening asthma control." (PMID 31992292, 2020). "Protein-protein interaction network data support the role of SMARCD1 in modulating asthma control while on ICS." (PMID 31992292, 2020). "That SMARCD1 interacts with age to affect asthma control on ICS, across two different cell types, in two different racial ancestry groups, and using two different measures of asthma control, indicates a robust effect." (PMID 31992292, 2020). "Age appears to modulate the effect of SMARCD1 on asthma control with inhaled corticosteroids." (PMID 31992292, 2020). "Furthermore, this effect was in the opposite direction as one might expect: SMARCD1 knockdown increased NF-kB, which generally increases inflammation, which generally increases asthma symptoms, and would lead to higher CAC." (PMID 31992292, 2020).
Borjeson-Forssman-Lehmann syndrome (1 paper, 2021). A X-linked yndrome characterized by intellectual deficit, truncal obesity, characteristic facial features, hypogonadism, tapered fingers and short toes. "Pathogenic variants in the BAF complex are known to cause CSS, Nicolaides-Baraitser syndrome (NCBRS, MIM 601358), Borjeson-Forssman-Lehmann syndrome (BFLS, OMIM 301900), and other CSS-like conditions (BICRA and SMARCD1)." (PMID 35126043, 2021).
endometrial carcinoma (1 paper, 2016). A malignant tumor arising from the epithelium that lines the cavity of the uterine body. "At the same time, we detect the expression level of c-Fos, nanog and SMARCD1 in the endometrial carcinoma cells transfected with miR-490-3p through RT-PCR and Western blotting." (PMID 26843615, 2016).